MYCN (MYCN proto-oncogene, bHLH transcription factor)
Diseases named in the same sentence as MYCN in open-access papers (continued):
Sharing a sentence is not in itself a finding about the gene and the disease.
tumor (continued). "We examined the transcriptional levels of key tumor-dependent genes (RUVBL1, GTF3C4, TIGD1, and TAF1A) between groups categorized by MYCN expression levels (low vs. high, n = 30 each) using Q-RT-PCR." (PMID 39175876, 2024). "The C13* signature effectively stratified tumours with a good and poor survival across the entire cohort even when corrected for INSS stage, MYCN amplification status, and age (Cox regression analysis with covariates)." (PMID 38702304, 2024). "All experiments were performed using two MYCN-amplified NB cell lines: SK-N-DZ derived from a metastatic site and IMR-32 derived from a primary tumor." (PMID 39715212, 2024). "The tumor promoting MYC, which is besides MYCN Proto-Oncogene, BHLH Transcription Factor (MYCN) and MYCL Proto-Oncogene, BHLH Transcription Factor (MYCL) part of the MYC transcription factor (TF) family, also impacts proliferation and malignant transformation." (PMID 38896334, 2024). "Nevertheless, MYCN was found to downregulate DPYSL3, possibly through the action of the enhancer of zeste homolog 2 (EZH2), which methylates histones of tumour suppressor genes." (PMID 38542729, 2024). "In the pediatric GBM, among the three tumor subtypes classified by DNA methylation landscape (MYCN, RTK1, and RTK2), it was found that MYCN was enriched for MYCN amplification, RTK1 enriched for PDGFRA amplification, and RTK 2 enriched for EGFR amplification." (PMID 38474286, 2024). "Introducing shear stress led to enhanced vascularization, culminating in the identification of tumor-derived endothelial cells expressing both CD31 and MYCN markers." (PMID 39872066, 2024). "Here, we demonstrate that upregulated KAP1 by MYCN interacts with YTHDC1 and protects YTHDC1 from ubiquitination and degradation, leading to enhanced tumor cell proliferation." (PMID 38745192, 2024). "MYCN tumours account for approximately 41% of this category, RTK1 are 38%, while RTK2 tumours are the rarest, at 21%." (PMID 39126064, 2024). "The results of RT-qPCR on 21 fresh tumor tissue samples of NB patients from our center further indicated a positive correlation between MTHFD1 and MYCN at the transcriptional level (R2 = 0.6690, P < 0.0001)." (PMID 38336749, 2024). "In conclusion, this study revealed the tumor-promoting role of MTHFD1 in NB, and elucidated the molecular mechanism by which MTHFD1 was directly transcriptionally regulated by MYCN." (PMID 38336749, 2024). "The upregulation of LIN28 accelerates the progression of various cancers via reciprocal regulation of the tumor suppressor miRNA, let-7, which suppresses oncogenes such as HMGA2, MYCN, and KRAS." (PMID 39420119, 2024). "Importantly, depletion of MYCN in MYCN-amplification NB induces the tumor cell apoptosis, differentiation and cell growth retardation, indicating that inhibiting MYCN by targeting its transcription and protein stability might be a therapeutic strategy for MYCN-amplification NB." (PMID 37543638, 2023). "As the results indicated, the expressions of CDCA3, MYCN and TFAP2A in ccRCC tumor tissue were significantly upregulated compared with those in adjacent normal kidney tissue, while the expressions of ACADSB and CHAC1 were significantly downregulated." (PMID 37064095, 2023). "The results obtained from both cohorts are very similar and clearly show that high expression of CCDC86 is found in patients with MYCN amplifications and the expression level of CCDC86 positively correlates with tumour stage progression and malignancy." (PMID 36695333, 2023). "Knocking down of lncUSMycN expression was shown to reduce MYCN at the mRNA and protein level, thereby inhibiting MNA NB cell proliferation and tumor growth in in vitro and in vivo NB models, respectively." (PMID 38069407, 2023).
tumor (continued). "To further clarify the effect of CCNB1IP1 on MYCN‐AM NB cell tumour growth, we constructed Ctrl‐, shMYCN‐ and shMYCN+CCNB1IP‐IMR‐32 cells‐derived subcutaneous xenograft tumour models." (PMID 37461251, 2023). "A similar trend was observed in tumor grade, where the expression levels of CENPA and TIMP1 were positively correlated with grade and that of MYCN was negatively correlated." (PMID 37213288, 2023). "A heatmap between normal and tumor tissues showed the expression of G6PD, HRAS, NRAS, TIMM9, and MYCN." (PMID 37143953, 2023). "However, consistent with the tumour growth phenotype, restoration of CCNB1IP1 expression did not effectively reverse tumour proliferation suppression caused by MYCN silencing, as evidenced by the unchanged Ki67 staining intensity in the shMYCN+CCNB1IP1OE group versus the shMYCN group." (PMID 37461251, 2023). "In this context, this article explores the role of the N-Myc, MYCN gene expression product on its target genes related to the cell cycle and reveals its regulatory network in promoting tumor proliferation and malignant progression." (PMID 36770809, 2023). "This study is the first to examine the SCNA status of both AH and tumor samples while simultaneously analyzing RB1, BCOR, CREBBP, and MYCN for SNV disease drivers." (PMID 37239954, 2023). "CNTFR mRNA expression in MNA–NB cells (Kelly) was reduced after BGA002 administration, which also extended the relationship between MYCN and CNTFR in another MYCN-related tumor." (PMID 36765949, 2023). "These abnormalities have been seen in both NB cell lines and tumours and are frequently demonstrated through FISH at the site of amplified copies of MYCN." (PMID 37958407, 2023). "In NB, attempts have been made to target MYCN‐MAX dimerization or inhibit MYCN‐MAX binding to DNA to block and arrest tumour development, and this has been a very long‐standing and relatively attractive perspective." (PMID 37461251, 2023). "To enhance the anti-tumor efficacy of KD + CP, with a view to exploit the OXPHOS capacity of MYCN-amplified cells, we also treated NB-xenograft-bearing mice with a triple therapy combination of KD, CP, and MET." (PMID 37623854, 2023). "Among them, MYCN amplification was also detected in the matched tumor sample (patient BC009), indicating that MYCN amplification in the urine was a true positive result." (PMID 37345205, 2023). "Importantly, our study reveals that GD2 expression on primary Th-MYCN tumor cells is stable through multiple rounds of engraftment and expansion, and provides proof-of-principle that transplant studies could facilitate detailed investigations of anti-NB immune activity and long-term protection." (PMID 37569447, 2023). "The accumulation of DAG appears to be an important protective mechanism for the tumor cells as it incorporates free fatty acids into TAG and lipid droplets and this phenomenon is mediated by MYCN via the upregulation of DGAT." (PMID 37046804, 2023). "MYCN, another member of the MYC gene family, is mainly involved in nervous system development and tumor formation." (PMID 38035110, 2023). "Comparatively, treatment reduced tumor volume in subcutaneous and orthotopic xenograft models of NB, as well as in the Th-ALKF1174L/MYCN-driven transgenic NB mouse model." (PMID 36839989, 2023). "Case 48 harbored a focal MYCN gain, which was detectable with both low-pass WGS and targeted tumor analyses." (PMID 37239954, 2023). "To verify that MYCMI-7 inhibits MYC:MAX dimerization in tumor cells, we utilized the split Gaussia princeps luciferase (GLuc) assay, with GLuc fragments GLuc1 and GLuc2 fused to MYC (or MYCN) and MAX, respectively, in HeLa cells." (PMID 36874405, 2022).
tumor (continued). "Samples of P07-aRMS were obtained at the same timepoint but showed different events: the primary tumour exhibited an ATRX-deletion, whilst the metastasis harboured SNVs in ATR and RAF1, a biallelic BCOR-deletion, and a MYCN-amplification." (PMID 36182817, 2022). "In murine tumor models, PIM kinases are weak oncogenes by themselves, but can exert strong cooperation with other oncogenes, in particular with MYC and MYCN in lymphomagenesis and prostate carcinogenesis." (PMID 36214609, 2022). "Let-7 serves as a potent tumor suppressor through post-transcriptional repression of a number of oncogenic mRNA targets including DICR1, ARID3B, HMGA2 and MYCN." (PMID 36505784, 2022). "Similar results were observed in another transgenic mouse model with Cre-conditional induction of MYCN in dopamine β-hydroxylase-expressing cells termed LSL-MYCN/Dbh-iCre, where clinically relevant NB tumor development occurred in 75% of mice." (PMID 36290282, 2022). "Hierarchical clustering based on the expression of the translation-related genes resulted in separate branch for MYCN-amplified tumors, including the MYCNARB1–/– tumor." (PMID 36245757, 2022). "In the FELIX and COG-N-561 PDXs, tumor growth was controlled by SHP099, Lastly, in the MHH-NB-11 MYCN-amplified model, tumor growth was controlled." (PMID 35905710, 2022). "As expected, TAM induction of Ezh2 deletion depleted MYCN, significantly inhibited expression of representative MYCN metabolic targets and uptake of the radiotracer 18F-deoxyglucose (FDG) to tumor sites, and dramatically prolonged the survival of TH-MYCN mice." (PMID 35013218, 2022). "The number of patients with high 3-O-MD expression was greater than zero in all subsets except for patients with stage L1 tumor, but it was higher in the subsets of patients older than 18 months, INRG stage M, and amplified MYCN tumors." (PMID 35756625, 2022). "CUDC-907 potently inhibits NB growth and 3D spheroid tumor growth by inhibiting PI3K, HDAC, and MYCN." (PMID 35205815, 2022). "Sympathetic neuroblasts respond to activated ALK with increased proliferation followed by neuron differentiation, but tumor induction requires a combination of activated ALK and MYCN overexpression or massive ALK over-expression." (PMID 35681734, 2022). "FN1 is a key gene in the RB tumor, and various works have confirmed that FN1 has been recognized to support cell proliferation and migration because it is correlated with MYCN." (PMID 36362243, 2022). "While MYCN is a well-recognized oncogene in several cancers including HCC46, MAP2K4 is reported to act as a tumor suppressor in HCC47." (PMID 35603298, 2022). "MYCN mRNA and protein expression was significantly reduced both in vitro and in vivo by metronomic topotecan, which also decreased VEGF-A expression and tumor vascularization." (PMID 36362482, 2022). "In particular, analysis of the hedgehog (HH) targets Gli1, MycN and Cyclin D2 proteins confirmed a similar SHH activity in the tumour samples of both backgrounds." (PMID 35839783, 2022). "We used CHLA136-Fluc (MYCN amplified) and CHLA255-Fluc (c-Myc overexpressed) to generate these xenograft mouse NB tumor models." (PMID 36428626, 2022). "An analysis of public functional genomics data showed that NB tumor viability depended on SMAD9, and its dependency score was potentially correlated with the MYCN amplification status and MYCN expression level." (PMID 36539767, 2022). "By taking the intersection of the two cohorts, we identified 26 upregulated TFs with twofold upregulation in tumour tissues compared with NT liver tissues, although four of them (E2F1, FOXM1, LIN28B, and MYCN) were excluded for overrepresentation." (PMID 36008383, 2022). "In an analysis of a highly specific AURKA inhibitor LY3295668 in 560 cancer cell lines, NB was among the most sensitive tumour type tested, with MYC/MYCN amplification identified as among the strongest predictors of sensitivity to this agent." (PMID 34195095, 2021).
tumor (continued). "While computational analyses are advancing our general knowledge of MB-tumour microenvironment (TME), the direct link between MYCN expression and TME profiling is still under investigation." (PMID 34195095, 2021). "As let-7 target c-MYC and MYCN and LIN28B is a transcriptional target of both c-MYC in multiple human and mouse tumor models and MYCN in NB, the inhibition of let-7 is c-MYC/MYCN-mediated via LIN28." (PMID 34771690, 2021). "Although differential expressions have been described in different tumour types, the MYC family proteins (MYC, MYCN and MYCL) have highly conserved domains, which suggests that the mechanisms through which they carry out tumorigenesis are similar." (PMID 33635497, 2021). "In an unbiased screen of a collection of 673 genetically characterized tumour-derived cellular models, NB cell lines were identified as among the most JQ1 sensitive and MYCN amplification as the most predictive marker of sensitivity." (PMID 34195095, 2021). "Considering that MYCN and TFRC are both deregulated in a variety of tumor types, our finding points to a tumor vulnerability that can be therapeutically exploited." (PMID 34011924, 2021). "MYCN is a transcription factor of the MYC family and is important for cell growth, apoptosis, tumor cell metabolism and normal cerebellar development." (PMID 33387268, 2021). "Seventy-six patient biopsies were grouped according to their tumor histological classification (CRPC or NEPC) and stratified into three categories based on RNA-seq values of MYCN expression (high vs. low) and RB1 genomic status (deletion, yes vs. no)." (PMID 34099734, 2021). "MYC is an uncommon driver of DIPG, and of the DIPG models tested here, SU-DIPGVI has a single copy of MYCN and c-MYC, while HSJD-DIPG007 is c-MYC amplified with a single MYCN copy, suggesting other driving factors in this tumor." (PMID 33579942, 2021). "It is impossible to know if the tumor even showed a TERT rearrangement since only a-CGH data were available; however, these rearrangements are almost mutually exclusive with MYCN amplification." (PMID 34830942, 2021). "Consistently, MYCN upregulation enhances the protein level of TfR1 in NB cells, which parallels with TFRC levels in NB tumor tissues." (PMID 34011924, 2021). "The dependence of the malignant phenotype on the presence of both MYCN and USP5 is highlighted by the marked antitumor effects of combination therapy and the low levels of both proteins in treated tumours." (PMID 33658627, 2021). "Histological and immunoblot analysis revealed small round blue cell tumours poor in stroma that expressed NCAM1, synaptophysin (SYP), Chromogranin A (CGA) and MYCN in Rosa26_Alkal2;Th‐MYCN tumours, in agreement with NB." (PMID 33411331, 2021). "We have previously shown that tumour growth of Th‐ALK‐F1174L;Th‐MYCN‐driven NB is inhibited by treatment with lorlatinib." (PMID 33411331, 2021). "MYC proteins play an important role in MB biology and often are dysregulated in all MB tumours, with MYC, MYCN and MYCL1 each showing commitment to specific subgroup." (PMID 34195095, 2021). "Immunoblot analysis of snap-frozen tumor tissues showed a decrease in ALYREF, USP3, and MYCN protein expression as a result of doxycycline treatment, compared to vehicle control." (PMID 33767157, 2021). "The Myc oncogenes (c-MYC, MYCN, MYCL) are important determinants of tumor progression in malignancies driven by their overexpression or amplification." (PMID 33915740, 2021). "Analysis of tumour size by ultrasound confirmed a robust tumour shrinkage in response to BAY 1895344 treatment at day 3 in both Rosa26_Alkal2;Th-MYCN and Alk-F1178S;Th-MYCN tumours." (PMID 34819497, 2021). "Unexpectedly, a therapeutic combination of an HDAC inhibitor (SAHA) and a novel pyridobenzimidazole (SE486-11) had profound anti-tumour effects and synergistically bound USP5, significantly reducing both USP5 and MYCN levels." (PMID 33658627, 2021).
tumor (continued). "This is further emphasized by the reactivation of the CLU gene by all the G9a inhibitors shown in our studies, as it is a NB tumor suppressor gene known to be regulated by EZH2 and MYCN." (PMID 32537432, 2020). "Further, we investigated the relationship between the expression of MYCN and DLEU2 in an independent set of NB primary tumors (Tumor NB public‐Westermann‐105‐ag44kcwolf) using the R2 database." (PMID 31637848, 2020). "Based on MYCN and DLEU2 expression in NB patients, survival curves were plotted and survival probability was estimated (Tumor NB public‐Versteeg‐88‐MAS5.0‐u133p2)." (PMID 31637848, 2020). "A significant reverse correlation was observed between the expression of E2F1 and MYCN mRNA and protein in OBP-301- and OBP-702-infected NB tumor cells." (PMID 32637577, 2020). "Usually, only one of these two MYC proteins can be expressed in a tumor cell at a time, with MYC often dominating over MYCN by repressing MYCN expression." (PMID 33585251, 2020). "The use of the MYCN inhibitors alisertib (MLN8237) and JQ1 can inhibit tumor growth, indicating that the MYCN gene is also involved in the tumorigenic process in HB." (PMID 32758256, 2020). "Specificity protein 1 (SP1)-induced HOXD-AS1 promoted tumor viability, metastasis, EMT, stemness and chemo-resistance in vitro and in vivo by sponging miR-520c-3p to increase oncogene MYCN." (PMID 32857725, 2020). "MYCN is an important member of the nuclear proto-oncogene MYC family, which supports the development of many different tumours, including retinoblastoma, medulloblastoma, prostate cancer, lung cancer and NB." (PMID 32034121, 2020). "In the NB xenograft model, ARV-825 profoundly reduced tumor growth and led to the downregulation of BRD4 and MYCN expression in mice." (PMID 33324552, 2020). "Introduction of CYCLIN D1 or MYCN overcomes this PAX-FOXO1-mediated cell cycle inhibition and promotes tumour growth." (PMID 33175861, 2020). "Other than the powerful performance of MYCN/NAGK ratio prediction, higher plasma MYCN/NAGK ratio showed consistent with heavier tumor load." (PMID 32896084, 2020). "The recently discovered MYC inhibitor 361 (MYCi361) binds to the HLH region of the MYC protein (AA366-378), disrupts MYC/MAX heterodimerization, enhances degradation of both MYC and MYCN, and suppresses MYC-dependent tumor cell growth in vitro and in vivo." (PMID 33628735, 2020). "Based on MYCN amplification status, age at diagnosis, INSS stage, histopathology, and tumor cell ploidy, NB patients are stratified into low-, intermediate-, and high-risk groups according to the 2007 COG risk system." (PMID 32974147, 2020). "While direct targeting of the MYCN transcription factor is not yet possible, several indirect methods have been proposed such as depleting MYCN protein levels with BET or AURKA inhibitors, but these appear to be with limited anti-tumor efficacy." (PMID 32211329, 2020). "Our current study revealed significant anti-tumor activity after HSP90 inhibition with the drug 17-AAG in the malignant, MYCN-amplified IMR-32 cells and more potent anti-tumor activity in the non-MYCN amplified SK-N-SH cells." (PMID 33569349, 2020). "In the tumours with partial 2p gain, the extra chromosomal segments varied in size from 25 to 130 Mb and included both ALK and MYCN except in 6 patients (data available on request)." (PMID 30778092, 2019). "High-level amplification of MYC and MYCN genes are also observed in GBM, and inhibition of Myc-induced glycolysis selectively killed MYC/MYCN-amplified patient-derived GBM tumor spheres and extended the survival of mice bearing MYCN-amplified PDX." (PMID 31450721, 2019). "For MYCN and ALK, this was evaluated by grouping tumor samples based on driver gene status (i.e. amplified and mutated respectively) followed by differential lincRNA expression analysis." (PMID 30952905, 2019).